SLC25A10 (solute carrier family 25 member 10)
Description:
Catalyzes the electroneutral exchange or flux of physiologically important metabolites such as dicarboxylates (malonate, malate, succinate), inorganic sulfur-containing anions, and phosphate, across the mitochondrial inner membrane. Substrate exchange across the membrane occurs consecutively with one substrate being transported first, then dissociating from the substrate binding site before the second substrate binds for transport in the opposite direction. Does not transport glutathione (By similarity). Plays an important role in gluconeogenesis, fatty acid metabolism, urea synthesis, and sulfur metabolism, particularly in liver, by supplying the substrates for the different metabolic processes. Regulates fatty acid release from adipocytes, and contributes to systemic insulin sensitivity (By similarity).
Synonyms: DIC; MTDPS19
Tractability: Antibody: UniProt predicts a signal peptide or a membrane-spanning region. PROTAC: ubiquitination databases record sites on it; its protein half-life has been measured.
Gene: Protein-coding gene on chromosome 17 (81,711,951 to 81,721,969, forward strand). Ensembl gene ENSG00000183048.
Subcellular location: Mitochondrion inner membrane
Subcellular location (Human Protein Atlas): Mitochondria; Nucleoplasm
Pathways (Reactome):
Metabolism: Sulfide oxidation to sulfate
Transport of small molecules: Organic anion transport by SLC5/17/25 transporters
Gene Ontology:
Molecular function: dicarboxylic acid transmembrane transporter activity; protein binding; malate transmembrane transporter activity; oxaloacetate transmembrane transporter activity; succinate transmembrane transporter activity; sulfate transmembrane transporter activity; thiosulfate transmembrane transporter activity; secondary active transmembrane transporter activity
Biological process: dicarboxylic acid transport; gluconeogenesis; malate transmembrane transport; oxaloacetate transport; phosphate ion transmembrane transport; succinate transmembrane transport; sulfate transmembrane transport; sulfide oxidation; thiosulfate transport; transmembrane transport; glyceraldehyde-3-phosphate biosynthetic process; oxaloacetate(2-) transmembrane transport
Cellular component: mitochondrion; nucleus; mitochondrial inner membrane
Genetic constraint (gnomAD): Loss-of-function variants: 32 observed, 36.41 expected, observed/expected ratio (o/e) 0.88, 90% interval 0.66 to 1.18. The upper end of that interval is the gene's LOEUF score, 1.18, which puts it in group 5 of 6, group 1 being the genes least tolerant of losing a copy. Missense variants: 394 observed, 385.64 expected, observed/expected ratio (o/e) 1.02, 90% interval 0.94 to 1.11. Synonymous variants: 181 observed, 162.32 expected, observed/expected ratio (o/e) 1.12, 90% interval 0.99 to 1.26.
Gene-disease validity (ClinGen):
ClinGen rates the evidence that SLC25A10 causes each of these diseases.
mitochondrial disease (autosomal recessive): Limited.
Homologues: Orthologues: guinea pig SLC25A10 (93% identical), macaque SLC25A10 (91% identical), mouse Slc25a10 (90% identical), rat Slc25a10 (89% identical), dog SLC25A10 (87% identical), pig SLC25A10 (86% identical), zebrafish slc25a10b (76% identical), tropical clawed frog slc25a10 (76% identical), rabbit SLC25A10 (72% identical), zebrafish slc25a10a (72% identical), chimpanzee SLC25A10 (70% identical), Caenorhabditis elegans slc-25A10 (55% identical), and 3 more. Paralogues in human: SLC25A11 (39% identical), SLC25A12 (30% identical), SLC25A13 (30% identical), SLC25A22 (29% identical), UCP2 (29% identical), UCP1 (28% identical), UCP3 (28% identical), SLC25A18 (28% identical), SLC25A30 (27% identical), SLC25A14 (26% identical), SLC25A47 (26% identical), SLC25A34 (25% identical), and 37 more.
Diseases named in the same sentence as SLC25A10 in open-access papers:
SLC25A10 is named in the same sentence as 29 diseases in open-access papers, as found by Europe PMC text mining. Sharing a sentence is not in itself a finding about the gene and the disease. The quoted sentences say what the papers report.
osteosarcoma (5 papers, 2021 to 2024). A usually aggressive malignant bone-forming mesenchymal neoplasm, predominantly affecting adolescents and young adults. "In individuals with osteosarcoma, higher expression of SLC25A10 was associated with unfavorable clinicopathological characteristics." (PMID 35518353, 2022). "Moreover, SLC25A10 may play an oncogenic role in human osteosarcoma, and high SLC25A10 expression was associated with poor clinicopathological parameters." (PMID 36114504, 2022). "SLC25A10 transports small metabolites by exchanging dicarboxylates for phosphate, sulfate, and other small molecules and functions as an oncogene in osteosarcoma, lung cancer, and breast cancers." (PMID 35288533, 2022). "SLC25A10 levels are elevated in human osteosarcoma tissues, compared with normal bone tissues; higher SLC25A10 levels have also been positively correlated with metastization." (PMID 34888300, 2021). "Further example includes SLC25A10, which operates as an oncogene in osteosarcoma." (PMID 35518353, 2022).
non-small cell lung carcinoma (4 papers, 2015 to 2024). A group of at least three distinct histological types of lung cancer, including non-small cell squamous cell carcinoma, adenocarcinoma, and large cell carcinoma. "It has been shown that abnormal expression of SLC25A10 would profoundly affect the proliferation of non-small cell lung cancer cells." (PMID 38568407, 2024). "Knockdown of SLC25A10 in non-small cell lung cancer cells alters growth characteristics to a less malignant phenotype and results in increased sensitivity to oxidative stress." (PMID 36855119, 2023). "Confluent non-small cell lung cancer (NSCLC) cell line A549 with downregulated SLC25A10 has altered growth behavior and decreased ability to respond to oxidative stress, especially in resting cells." (PMID 32455902, 2020). "Here, we investigated the effects of decreased expression of SLC25A10 on cell growth, NADPH production and redox homeostasis in the non-small cell lung cancer (NSCLC) cell line A549." (PMID 25797253, 2015).
colorectal cancer (3 papers, 2024 to 2025). A primary or metastatic malignant neoplasm that affects the colon or rectum. "Conversely, a broad investigation into metastasis-associated genes in colorectal cancer proposed that MRPL19 was associated with decreased metastasis risk through SLC25A10 and MRPL1." (PMID 39354291, 2024). "Contrarily, MRPL37 was associated with metastasis inhibition in colorectal cancer, with interactions with SLC25A10 through MRPL1 also identified." (PMID 39354291, 2024). "One study found that MRPL37 is associated with metastasis inhibition in colorectal cancer, with interactions between MRPL37 and SLC25A10 through MRPL1 reinforcing its synergistic role." (PMID 41399509, 2025). "Likewise, in colorectal cancer, analysis of genes associated with metastasis found that MRPL38 was associated with lower levels of metastasis through SLC25A10." (PMID 39354291, 2024).
cardiac ischemia (2 papers, 2024). "Moreover, we found an emerging role of MPV17 in protecting cardiomyocytes from iron overload-induced ferroptosis and attenuating cardiac ischemia/reperfusion (I/R) injury through maintaining the protein homeostasis of SLC25A10, which imports GSH from the cytosol into the mitochondria." (PMID 39409161, 2024).
Anxiety (1 paper, 2018). Intense feelings of nervousness, tension, or panic often arise in response to interpersonal stresses. "The Slc25a10 gene may be involved in some 1000 central nervous system diseases such as mood disorders, anxiety, depression and others." (PMID 30537945, 2018).
Graves disease (1 paper, 2024). Graves' disease is an autoimmune disorder that leads to overactivity of the thyroid gland (hyperthyroidism).It is caused by an abnormal immune system response that causes the thyroid gland to produce too much thyroid hormones. "The analysis identified several mitochondrial proteins downregulated by HFD, including the citrate carrier (SLC25A1), the dicarboxylate acid carrier (SLC25A10), a glutamate carrier (SLC25A22), and a carrier associated with Graves’ disease (SLC25A16)." (PMID 39111307, 2024).
Insulin resistance (1 paper, 2017). Increased resistance towards insulin, that is, diminished effectiveness of insulin in reducing blood glucose levels. "By transcriptome profiling in a large human cohort including non-obese and obese with or without insulin resistance, combined with functional evaluation in adipocyte cultures of specific genes, this study identifies KLF15 and SLC25A10 as potential modulators of adipocyte insulin sensitivity." (PMID 28570579, 2017).
iron overload (1 paper, 2024). "This evidence demonstrated that SLC25A10 prevented iron overload-induced myocardial ferroptosis." (PMID 39409161, 2024).
lung adenocarcinoma (1 paper, 2021). A carcinoma that arises from the lung and is characterized by the presence of malignant glandular epithelial cells. "The knockdown of SLC25A10 changes the growth properties to a less malignant phenotype and causes increased glutamine dependency and sensitivity to oxidative stress in human lung adenocarcinoma cells, suggesting SLC25A10 as a novel target for anticancer strategies." (PMID 34568013, 2021).
ovarian carcinoma (1 paper, 2022). A malignant neoplasm originating from the surface ovarian epithelium. "Results showed that low expression of SLC25A10 was associated with the poor survival time in ovarian cancer patients from TCGA dataset." (PMID 36114504, 2022). "To further understand how SLC25A10 is involved in ovarian cancers, we employed GO analysis to figure out SLC25A10-associated pathways." (PMID 36114504, 2022). "In this study, we found that SLC25A10 expression was associated with low-risk score of ovarian cancers." (PMID 36114504, 2022). "In sum, we developed a 16-gene prognostic signature, which could serve as a promising tool for the prognostic prediction of ovarian cancer, and the expression level of SLC25A10 was tightly associated with OS of the patients." (PMID 36114504, 2022). "Based on the findings that higher SLC25A10 was associated with better prognosis in ovarian cancer patients, we assumed that elevated SLC25A10 expression may be beneficial to improve the overall survival time of patients." (PMID 36114504, 2022). "Moreover, we identified SLC25A10, a gene encodes a mitochondrial dicarboxylate transporter, as an excellent prognostic marker and potential therapeutic target for ovarian cancers." (PMID 36114504, 2022). "In addition to the identification of the risk score model, we also pinpointed that SLC25A10 may be a good prognostic marker and therapeutic target for ovarian cancers." (PMID 36114504, 2022). "The relationship between the prognosis of ovarian cancer and the expression level of SLC25A10 was selected for further analysis." (PMID 36114504, 2022). "To test this hypothesis, we analyzed the OS of ovarian cancer patients based on SLC25A10 expressions." (PMID 36114504, 2022). "Moreover, the Kaplan-Meier analysis further confirmed that high SLC25A10 expression was correlated with better prognosis for ovarian cancer patients." (PMID 36114504, 2022). "Moreover, we pinpointed that SLC25A10 as a novel indicator for prediction of patient prognosis in ovarian cancers, and provided potential chemotherapeutic strategy for tumor treatment." (PMID 36114504, 2022). "Interestingly, the gene-drug analysis showed that the sensitivity of ovarian cancer tumor cells to most chemotherapeutic agents was also diminished by low SLC25A10 expressions; however, Pluripotin, ARRY-162 and Pimasertib were more sensitive to low SLC25A10 cells." (PMID 36114504, 2022).
prostate carcinoma (1 paper, 2025). A carcinoma that arises from epithelial cells of the prostate gland. "Collectively, our findings uncover a novel oncogenic role of SLC25A10 in PCa and suggest that targeting the SLC25A10-mediated regulatory network may offer a promising therapeutic avenue for patients with advanced prostate cancer." (PMID 40393974, 2025).
thrombophilia (1 paper, 2023). A condition characterized by an abnormally high level of thrombi. "Within this subnetwork, SLC25A10 is the only gene known to be involved in thrombophilia, according to DisGeNet." (PMID 37098010, 2023).
urinary bladder cancer (1 paper, 2023). A primary or metastatic malignant neoplasm involving the bladder. "The roles of ABCC5, ABCA8, ABCC10, ABCB10, ABCG1, ATP7B, ABCG2, and mitochondrial SLC25A10 in platinum-receiving urinary bladder cancer patients should be the subject of further investigation." (PMID 36650399, 2023).
cancer (10 papers, 2015 to 2025). A tumor composed of atypical neoplastic, often pleomorphic cells that invade other tissues. "It was reported to be highly expressed in most human cancers (e.g., thyroid, colorectal, prostate, ovarian, etc.), and is strongly associated with poor cancer prognosis.SLC25A10 is upregulated in a variety of tumors and is involved in regulating intracellular levels of reactive oxygen species." (PMID 36855119, 2023). "In 13/20 tumor types, SLC25A10 exhibited >2-fold increase in cancer expression as compared to stromal cells." (PMID 36114504, 2022). "The contribution of SLC25A10 to reprogram cell metabolism and to regulate cell growth suggests SLC25A10 as a novel target for anti-cancer strategies." (PMID 25797253, 2015). "This work suggests that the mitochondrial carrier SLC25A10 is of importance for the properties that characterize cancer cells and hypothetically could be used as a target for that kind of regulation." (PMID 25797253, 2015). "We suggest SLC25A10 as a novel target to be exploited in the ongoing challenge to combat cancer." (PMID 25797253, 2015). "Finally, to investigate the significance of SLC25A10 for the activity of anti-cancer compounds, the sensitivity of cisplatin and 2′, 2-difluoro-deoxycytidine (dFdC) were determined." (PMID 25797253, 2015). "Interestingly, while the exact role of SLC25A10 in tumor cells remains unclear, an increase in SLC25A10 expression has been confirmed in various types of cancer." (PMID 40393974, 2025). "The SLC25A10 knockdown cells were also more sensitive to the anti-cancer drug cisplatin, but not to the nucleoside analog dFdC." (PMID 25797253, 2015). "In addition to SLC25A10, other mitochondrial carriers of the SLC25 family are also involved in cancer." (PMID 25797253, 2015). "Overall our study proposes the importance of a functional SLC25A10 carrier to maintain properties of cancer cells, such as NADPH production independent of the PPP pathway." (PMID 25797253, 2015).
tumor (7 papers, 2015 to 2025). "Restoring SLC25A10 expression partly reversed the reduced tumor volume and weight caused by INHBA knockdown, whereas silencing SLC25A10 partly attenuated the tumor volume and weight enhancements due to INHBA upregulation." (PMID 41449244, 2025). "Functional gain- and loss-of-function experiments demonstrated that SLC25A10 promotes tumor cell proliferation, migration, and invasion, while exacerbating mitochondrial dysfunction and impairing autophagic flux." (PMID 40393974, 2025). "We observed that SLC25A10 is significantly expressed in epithelial cells in tumor, indicating its potential role in regulating mitochondrial function and substance transport in epithelial cells." (PMID 40393974, 2025). "A subcutaneous xenograft tumor model was used to further investigate the impact of SLC25A10/p62/KEAP1/Nrf2 on tumor growth in vivo." (PMID 40393974, 2025). "The results clearly demonstrated a significant overexpression of SLC25A10 in the PCa tumor tissues compared to the normal samples." (PMID 40393974, 2025). "The migration of tumor cells is closely associated with the epithelial–mesenchymal transition (EMT) process, prompting us to explore the relationship between EMT and SLC25A10." (PMID 40393974, 2025). "To further verify the in vivo role of SLC25A10, we subcutaneously transplanted syngeneic tumor into C57BL/6 mice." (PMID 41449244, 2025). "IHC results further confirmed this, showing a significant increase in the proportion of Ki67-positive cells in the tumors of the SLC25A10-overexpressing mice, indicating enhanced proliferative activity of tumor cells." (PMID 40393974, 2025). "Consistent with the in vitro findings, knocking down Nrf2 markedly inhibits the tumor growth induced by the upregulation of SLC25A10." (PMID 40393974, 2025). "We propose SLC25A10 as a novel target for anti-tumor compound development with the aim to reprogram cell metabolism, compromise cell growth and increase sensitivity to the important anticancer drug cisplatin." (PMID 25797253, 2015). "Based on the evidence of altered expression of SLC25A10 in tumor cells we were interested in the role of SLC25A10 to maintain the growth properties of tumor cells in culture." (PMID 25797253, 2015). "Furthermore, knocking down Nrf2 expression in cells overexpressing SLC25A10 significantly suppresses tumor cell proliferation and migration." (PMID 40393974, 2025). "This implies that SLC25A10 may play a regulatory role in mitochondrial function and substance transport within epithelial cells, thereby promoting tumor progression." (PMID 40393974, 2025). "Furthermore, heightened SLC25A10 levels foster tumor cell proliferation and migration while inducing disturbances in mitochondrial morphology and inhibiting autophagy within the cells, ultimately driving the progression of PCa." (PMID 40393974, 2025). "As expected, the overexpression of SLC25A10 significantly promoted tumor growth, which could be reversed by knocking down Nrf2." (PMID 40393974, 2025). "Additionally, HE staining revealed that the tumors in SLC25A10-overexpressing mice displayed a more compact tissue structure, suggesting enhanced tumor proliferation." (PMID 40393974, 2025). "Notably, the reintroduction of SLC25A10 into PCa cells with silenced SLC25A10 significantly reversed the tumor-suppressive effects it mediated." (PMID 40393974, 2025). "For example, a study found that the expression of SLC25A10 could reprogram tumor metabolism, affect its growth, and enhance the sensitivity of tumor cells to chemotherapeutic drugs such as cisplatin, which was considered a new therapeutic target." (PMID 36254139, 2022). "Notably, the promotion of tumor growth by SLC25A10 was significantly reversed upon silencing Nrf2." (PMID 40393974, 2025). "Interestingly, increased SLC25A10 expression has been seen in a variety of tumor types." (PMID 32455902, 2020).
tumor (continued). "Interestingly, metformin treatment decreased the expression of the SLC25A10 carrier, suggesting that this drug could inhibit tumor growth when used in cancer treatment." (PMID 32455902, 2020). "This potential mechanism may involve SLC25A10’s disruption of ferroptosis in tumor cells through the regulation of the p62/KEAP1/Nrf2 pathway, thereby promoting the survival of tumor cells." (PMID 40393974, 2025). "Importantly, we show that INHBA maintains mitochondrial SLC25A10 stability, thereby activating the succinate/SUCNR1 axis and the mtGSH/GPX4 axis to promote tumor malignancy." (PMID 41449244, 2025). "We subsequently performed subcutaneous syngeneic tumor transplantation experiments in C57BL/6 mice via mouse cell models with INHBA knockdown and restored SLC25A10 expression, as well as models with INHBA overexpression and SLC25A10 knockdown." (PMID 41449244, 2025). "Interestingly, increased SLC25A10 expression has been demonstrated in a variety of tumors although the exact role of SLC25A10 in tumor cells is not known." (PMID 25797253, 2015).
SLC25A10 also shares sentences with these, for which no sentence is quoted: breast carcinoma (4 papers); lung carcinoma (2); cardiac diseases (1); central nervous system diseases (1); depression (1); diabetes (1); dilated cardiomyopathy (1); juvenile idiopathic arthritis (1); liver cancer (1); metabolic disorders (1); metabolic syndrome (1); mood disorder (1); myeloma (1); Obesity (1).